ENSG00000201882
Gene: Small nucleolar RNA gene on chromosome X (20,136,066 to 20,136,135, reverse strand). Ensembl gene ENSG00000201882.
Gene Ontology:
Biological process: RNA processing
Cellular component: nucleolus
Homologues: Orthologues: rat LOC120100394 (87% identical), mouse Gm54904 (70% identical).